CRB1 (crumbs cell polarity complex component 1)
Diseases named in the same sentence as CRB1 in open-access papers (continued):
Sharing a sentence is not in itself a finding about the gene and the disease.
autosomal recessive disease (1 paper, 2018). Autosomal recessive form of disease. "Other more representative genes were CEP290, USH2A, and CRB1 that caused autosomal recessive diseases and RPGR and CHM that caused X-linked IRD; each one accounted for about 5% of the conclusive results." (PMID 30374144, 2018).
infection (1 paper, 2023). The state of being infected such as from the introduction of a foreign agent such as serum, vaccine, antigenic substance or organism. "Furthermore, the infection of AAV.hCRB1 on the CRB1KO retinal organoids shows localization of recombinant CRB1 protein at the OLM." (PMID 37084726, 2023).
inherited diseases (1 paper, 2025). "In recent studies, similar approaches were developed to activate the genes associated with various inherited diseases, including CRB1 (RP) and USH2A, in human skin fibroblasts." (PMID 41056201, 2025).
CRB1 also shares sentences with these, for which no sentence is quoted: Stargardt disease (5 papers); Nystagmus (4); achromatopsia (2); cone dystrophy (2); Familial exudative vitreoretinopathy (2); Leber congenital amaurosis 8 (2); myopia (2); primary angle-closure glaucoma (2); retinitis pigmentosa 12 (2); tumor (2); X-linked juvenile retinoschisis (2); amblyopia (1); aneurysm (1); angle-closure glaucoma (1); Bardet-Biedl syndrome (1); choroidal neovascularization (1); choroideremia (1); corneal dystrophy (1); Doyne honeycomb retinal dystrophy (1); dysplasia (1); Hypermetropia (1); incontinentia pigmenti (1); intermediate uveitis (1); isolated macular dystrophy (1); melanoma (1); myocardial infarction (1); neovascular glaucoma (1); Obesity (1); Photophobia (1); pigmented paravenous chorioretinal atrophy (1).
A further 7 diseases each share a sentence with CRB1 in 1 paper.